VEGFA (vascular endothelial growth factor A)
Diseases named in the same sentence as VEGFA in open-access papers (continued):
Sharing a sentence is not in itself a finding about the gene and the disease.
liver cancer (continued). "Thus, inhibiting VEGFA produced by LCSCs is a feasible and effective way to block the angiogenesis of residual liver cancer after iRFA treatment." (PMID 33145353, 2020). "Our study demonstrated that Manilkara zapota leaf water extract upregulates JNK1 and iNOS and transcriptional downregulation of ERK1/2, Akt1, and VEGFA expression implies the potential use of Manilkara zapota leaf water extract in future applications to combat liver cancer." (PMID 30519270, 2018). "Moreover, increased VEGFA has been observed in HBV-related liver cancer." (PMID 36193503, 2022). "Thus, we speculated that the effect of Xihuang pill on liver cancer might be realized by targeting VEGFA and EGFR in pathways like proteoglycans in cancer and estrogen signaling." (PMID 32256653, 2020). "Furthermore, the effect of Xihuang pill on liver cancer might be realized by targeting VEGFA and EGFR in pathways like proteoglycans in cancer and estrogen signaling." (PMID 32256653, 2020). "For example, in liver cancer, miR‐138‐5p inhibits vascular simulation in HepG2 and Hep3B cells by suppressing the HIF‐1α/VEGFA signalling pathway." (PMID 40735832, 2025). "Research has shown that under hypoxic conditions, HIF-1α transcriptionally activates the VEGF A VEGFA gene, promoting blood vessel formation in liver cancer." (PMID 40190273, 2025). "We found that upon knockdown of several ligands (VEGFA, ITGB3BP and ADAM9) in M2 macrophages, there was significant reduction in at least one of the liver cancer stem cell markers tested." (PMID 38169544, 2024). "Lower panel: Elevated CHI3L1 levels increase VEGFA expression through the ERK1/2 and Akt pathways, promoting angiogenesis in liver cancer." (PMID 38177294, 2024). "In summary, seven of the genes (VEGFA, CTNNB1, SPP1, PPARG, RAC1, HSP90AA1, and LGALS3) were highly unregulated in patients with liver cancer." (PMID 35069936, 2022). "In the current study, VEGFA and EGFR were not only overlapping genes revealed between Xihuang pill target sets and liver cancer target sets but also hub nodes in PPI modules." (PMID 32256653, 2020). "Experimental studies have also confirmed that in vitro experiments after Pachyman treatment showed that the cellular content of VEGFA protein decreased while the intracellular level of ALB protein increased, ultimately confirming the positive effect of Pachyman on liver cancer." (PMID 39806972, 2025). "Moreover, mutation at position 312 of ASH2L significantly diminished the ability of AARS1 to enhance VEGFA expression in HCC cells, indicating that AARS1 promoted angiogenesis in liver cancer through ASH2L lactylation." (PMID 40726441, 2025). "Research on the liver cancer signaling pathway has revealed that bone morphogenetic protein 9 (BMP9) and inhibitor of DNA binding 1 (ID1) can activate the expression of HIF-1α and VEGFA, which affects the angiogenesis of liver cancer lesions." (PMID 39619441, 2024). "To assess whether R848 plays a similar role in liver cancer, we selected two tumor vascular markers—CD31 and VEGFA—for immunohistochemical staining of tumor tissues." (PMID 35719978, 2022). "In patients with liver cancer complicated by depression, IGF1/VEGFA/SERPINE1 may play an important role in the pathogenesis and development of the disease, but the specific mechanism has not been clarified." (PMID 33960267, 2021). "Thus, the expression trend for VEGFA and CD31 in the iRFA-liver cancer samples was similar to that for CD133, indicating that angiogenesis was promoted by LCSCs induced by iRFA." (PMID 33145353, 2020).
liver cancer (continued). "In addition, miR-203 downregulation has been described in various cancers including esophagus, cervix, prostate, breast, and liver cancer, and miR-203 inhibits cancerous invasion by targeting SNAI1, SNAI2, ZEB2, and VEGFA." (PMID 26882562, 2016). "Just as monocytes produce migrasomes rich in VEGFA and CXCL12 to promote angiogenesis under physiological conditions, migrasomes from highly metastatic liver cancer cells also have high concentrations of VEGFA, further promoting angiogenesis and distant metastasis in mice with liver cancer." (PMID 40443653, 2025). "VEGFA and EGFR might be potential therapy targets of Xihuang pill in liver cancer." (PMID 32256653, 2020). "Thus, we speculated that genes such as VEGFA and EGFR might be potential therapy targets of Xihuang pill in liver cancer." (PMID 32256653, 2020). "In conclusion, VEGFA and EGFR might be potential therapy targets of Xihuang pill in liver cancer." (PMID 32256653, 2020).
ischemic stroke (206 papers, 2010 to 2026). A stroke disorder caused by obstruction of blood flow to the brain, due to thrombotic (local blood clot formation) or embolic (due to a blood clot or other material traveling from another site) event. "A very promising process to target therapeutically is driven by vascular endothelial growth factor A (VEGF), which has long been implicated in the regulation of several events that take place following ischemic stroke, the leading cause of acquired disability in the developed world." (PMID 31312121, 2019). "However, the effects of the VEGFA polymorphisms on the outcome of ischemic stroke (IS) have been rarely reported." (PMID 28234972, 2017). "We identified that the angiotensin receptor antagonist, candesartan, has profound neurovascular protective properties when administered after ischemic stroke and was associated with a proangiogenic state at least partly explained by vascular endothelial growth factor A (VEGFA)." (PMID 21912702, 2011). "The evidence indicates that the therapeutic effect is exerted via the HIF-1α/EPO/VEGFA signaling pathway with regard to ischemic stroke." (PMID 40166460, 2025). "Despite its beneficial effects such as facilitating reparative angiogenesis, and providing neuroprotection in the aftermath of ischemic stroke, VEGFA demonstrates certain limitations." (PMID 38468126, 2024). "Several studies have shown decreased levels of VEGFA in Alzheimer’s disease, while ischemic stroke patients have elevated levels post symptom onset." (PMID 37550790, 2023). "Serum miRNA levels, brain-derived neurotrophic factor (BDNF) and vascular endothelial growth factor A (VEGF-A) were assessed at admission and 24 and 72 h after a post-ischemic stroke, and were compared to 20 controls." (PMID 33076256, 2020). "For example, Ranibizumab can target VEGFA and regulate the two pathways of hsa04151 and hsa05200 to play the role of immunomodulation after ischemic stroke, and may provide a basis for the following mechanism research." (PMID 35419038, 2022). "Furthermore, VEGFA‐mediated neurovascular protection and Notch‐1‐triggered antiapoptotic effects in endothelium and other neural cells may synergistically contribute to neurovascular protection during the acute stage of ischemic stroke." (PMID 36786352, 2023). "IL-6, AKT1, VEGFA, STAT3, TNFα, etc., were the core target of phenolic acids in preventing ischemic stroke." (PMID 36778026, 2023). "Vascular endothelial growth factor A (VEGF-A) is a crucial cytokine responsible for the regulation of angiogenesis, which promotes neurogenesis and nerve function recovery after ischemic stroke." (PMID 37287803, 2023). "VEGFA can increase microvascular permeability and endothelial cell migration, thus enhancing angiogenesis in the ischemic organ and reducing IRI, becoming a research hotspot and potential target of ischemic stroke." (PMID 35698607, 2022). "Based on network pharmacological analysis, the core targets of AS-TMP combination for anti-ischemic stroke are TIMP-1, VEGFA, MMP9, etc., which are mainly related to apoptosis, cell proliferation, and vascular smooth muscle cell proliferation, focusing on the VEGF signaling pathway." (PMID 40869300, 2025).
Cerebral ischemia (204 papers, 2006 to 2025). Restriction of arterial blood supply to the brain associated with insufficient oxygenation to support the metabolic requirements of the tissue. "Our experimental findings demonstrated that activation of NF-κB phosphorylation in brain microvascular endothelial cells during repairing cerebral ischemia led to upregulating VEGFA expression." (PMID 38995444, 2025). "The differential expression of IGF-2, TIMP-2, VEGFA, and bFGF observed in our study highlights the complex nature of the biological response to cerebral ischemia and the potential influence of therapeutic interventions." (PMID 38178130, 2024). "During cerebral ischemia, vascular endothelial growth factor-A (VEGF-A) secreted by astrocytes directly disrupted the blood-brain barrier." (PMID 38543171, 2024). "Cardamonin has significant anticancer, anti-inflammatory, and antioxidant activities and neuroprotective effects and can attenuate cerebral ischemia/reperfusion injury through activation of the HIF-1α/VEGFA pathway." (PMID 39359632, 2024). "VEGFA is vascular endothelial growth factor A. VEGFA can promote the proliferation and division of vascular endothelial cells after cerebral ischemia." (PMID 34889224, 2021). "Given that vascular endothelial growth factor A (VEGF-A), a key factor for the vascular response to cerebral ischemia, is a direct, bona fide HIF-1 target gene, we monitored cerebral cortical blood flow (CBF) during and after transient cerebral ischemia in vivo." (PMID 38773968, 2024). "However, many studies have demonstrated the protective role of VEGFA in brain disorders, such as cerebral ischemia/reperfusion injury and traumatic brain injury." (PMID 37573538, 2024). "Similarly, partial increases in VEGFA stimulate vasodilation, angiogenesis and neuroprotection mechanisms, which are beneficial for the brain in later stages after cerebral ischemia." (PMID 35625687, 2022). "In addition, vascular endothelial growth factor A (VEGFA) is recognized as a hypermethylated RNA; VEGFA is a factor that is closely related to angiogenesis after cerebral ischemia, and hypermethylated VEGFA can promote angiogenesis through multiple pathways." (PMID 36479246, 2022). "When cerebral ischemia occurs, VEGFA is markedly upregulated in the ischemic penumbra area." (PMID 34054530, 2021). "Additionally, studies have revealed that the activation of VEGFA on brain microvascular endothelial cells could mitigate cerebral ischemia/reperfusion injury." (PMID 38995444, 2025). "However, early VEGFA increases may lead to undesirable effects in cerebral ischemia, such as an increase in blood–brain barrier permeability and infiltration of immune cells inducing neuroinflammation and edema." (PMID 35625687, 2022). "Therefore, we speculate that HH can regulate VEGFA, VEGFR2, and eNOS via the pathways associated with promote angiogenesis and alleviate cerebral ischemia injury." (PMID 33953789, 2021). "We also focused on the role of VEGFA in the combined AS and TMP treatment of experimental cerebral ischemia, as this target was identified in the results of network pharmacology." (PMID 40869300, 2025). "Similar changes were observed in an in vivo model, with CGS21680 leading to a significant increase in VEGFA and VEGFR2 expression in the corpus callosum of rats with CCH, especially as the duration of cerebral ischemia increased." (PMID 40615465, 2025). "The inhibition of VEGFA and its receptor VEGFR2 has been proven to ameliorate cerebral ischemia-induced BBB dysfunction." (PMID 40615465, 2025). "We also examined the mRNA expression of VEGFA and VEGFB in mice and bEnd.3 cells, observed that levels of both were upregulated following cerebral ischemia/reperfusion." (PMID 36909178, 2023).
Cerebral ischemia (continued). "VEGFA is a member of the VEGF family of vascular endothelial growth factors, which plays an important role in the process of angiogenesis after cerebral ischemia, and the administration of VEGFA to the MCAO rat model can increase neuroprotective effects." (PMID 34754318, 2021). "Furthermore, through the pharmacological experiment, we predict that HH can regulate VEGFA, VEGFR2, and eNOS via the HIF-1 signaling pathway and VEGF signaling pathway to promote angiogenesis and alleviate cerebral ischemia injury." (PMID 33953789, 2021). "Our results predict that HH may regulate the expression of VEGFA, VEGFR2, and eNOS via the VEGF and HIF-1 signaling pathway to promote angiogenesis and alleviate cerebral ischemia injury." (PMID 33953789, 2021). "In this study, the expression levels of phosphorylated (p)-Src, VEGFA and claudin-5 were determined to investigate the changes occurring in the levels of these proteins and to determine the benefits of PP2 treatment following cerebral ischemia/reperfusion (I/R)." (PMID 25269821, 2014).
breast tumor (199 papers, 1999 to 2026). "Furthermore, we demonstrated that VEGFa expression in and secretion from breast tumor cells are positively associated with the manipulated NCOA1 expression levels, suggesting that NCOA1 tightly regulates VEGFa expression in these tumor cells." (PMID 26287601, 2015). "Recently, researchers demonstrated that ZNF24 bound to the promoter of VEGFA and inhibited its transcription then suppressed breast tumor growth via repressing angiogenesis." (PMID 34480024, 2021). "NCOA1 promotes angiogenesis in breast tumors by enhancing the transcription of VEGFa via HIFα and AP-1." (PMID 33167967, 2020). "As a downstream event, ILK upregulates vascular endothelial growth factor A (VEGF-A), thus promoting angiogenesis and the dissemination of breast tumor cells." (PMID 33371274, 2020). "Breast tumors with this angiogenic profile (approximately, 28% of all cases) showed a particularly high expression of VEGFA and miR-20a (p<0.0001)." (PMID 29617404, 2018). "This is consistent with the role of NCOA1 in upregulating VEGFa to stimulate angiogenesis in human breast tumors." (PMID 26287601, 2015). "Furthermore, upregulated miR-182 under hypoxia induces vascular endothelial growth factor A (VEGFA) expression downstream of HIF1-signaling to promote angiogenesis in breast tumors." (PMID 37583933, 2023). "Similarly, miR-20a and 20b are also differentially distributed within breast tumor mass, along with the opposite expression patterns of HIF1α and VEGFA in these tumors." (PMID 37583933, 2023). "CITED-2 regulates/attenuates primary breast tumor growth, likely by influencing tumor vasculature via TGF-beta-dependent regulation of VEGFA." (PMID 39859448, 2025). "Immunohistochemistry was used to evaluate VEGFA and MIF levels in breast tumors and normal breast tissues; qPCRs and western blots were used to validate the expression of clinical immuno-oncology (IO) therapeutic targets CD274 (PD-L1) and IL8 in cell lines." (PMID 31293831, 2019). "Collectively, these data indicate that CITED2 regulates primary breast tumor growth, likely by influencing tumor vasculature via TGF-β-dependent regulation of VEGFA." (PMID 28008154, 2017). "Furthermore, BRCA1/2-related breast cancers also presented a higher percentage of VEGFA, HIF1A, FAK and ANGPT2 gene overexpression compared to the BRCAX breast tumour group (VEGFA: 62% vs 9%, p=0.04; HIF1A: 62% vs 0%, p=0.004; FAK: 62% vs 18%, p=0.073; ANGPT2: 50% vs 45%, p= 1.00)." (PMID 25333258, 2015).
metastatic colorectal cancer (193 papers, 2004 to 2026). "We previously reported the association of VEGFA rs833061 C/T variants with PFS in metastatic colorectal cancer patients treated with first-line FOLFIRI plus bevacizumab." (PMID 23861747, 2013). "For example, the use of anti-angiogenic therapies, which target the formation of new blood vessels, has proven successful in cancer treatment, with anti-VEGFA antibodies currently being used to treat patients with metastatic colorectal cancer." (PMID 37398649, 2023). "In 2004, the American FDA granted an unprecedented approval to a humanized anti-VEGFA monoclonal antibody, named as bevacizumab, to treat patients with metastatic colorectal cancer." (PMID 36324128, 2022). "Owing to the extensive research on VEGF, the VEGFA (vascular endothelial growth factor A) inhibitor bevacizumab was authorized by the Food and Drug Administration for the first-line treatment of metastatic colorectal cancer in 2004." (PMID 36479043, 2022). "Bevacizumab, which is a monoclonal antibody frequently used in the treatment of metastatic colorectal cancer, binds to the ligand of vascular endothelial growth factor A (VEGFA) and inhibits tumor angiogenesis." (PMID 36422502, 2022). "Bevacizumab, a recombinant humanised anti-vascular endothelial growth factor-A (VEGF-A) monoclonal antibody, is an approved anti-angiogenic drug which is used in combination with chemotherapy for the treatment of metastatic colorectal cancer (mCRC)." (PMID 35075138, 2022). "In metastatic colorectal cancer (mCRC), expression of E-cadherin in either cell membrane or cytoplasm was combined with strong vascular endothelial growth factor A (VEGF-A) staining as a predictor of disease outcome." (PMID 33076339, 2020). "High serum levels of VEGFA and placental growth factor PlGF may be the basis of bevacizumab resistance in patients with metastatic colorectal cancer." (PMID 38687357, 2024). "Among targeted agents approved for treatment of metastatic colorectal cancer, the impact of bevacizumab, a monoclonal antibody against the vascular endothelial growth factor A (VEGF-A) on liver histology and perioperative complications is of particular interest." (PMID 26864935, 2016). "VEGFA has been reported to promote tumor metastasis, and TAN were found to counteract anti-VEGF therapy in metastatic colorectal cancer." (PMID 37931958, 2024). "Detection of the expression levels of VEGFA and VEGFR2 in blood samples of patients with metastatic colorectal cancer are a direct and accurate method to monitor the effects of anti-angiogenesis therapy." (PMID 36364081, 2022). "In this context, the monoclonal antibody designed against vascular endothelial growth factor-A (VEGF-A) (bevacizumab) was the first US Food and Drug Administration (FDA)-approved anti-angiogenic drug for the treatment of metastatic colorectal cancer." (PMID 29342121, 2018). "This resulted in the development of the recombinant humanized VEGFA-specific mAb bevacizumab, which was approved by the US FDA in 2004 for the first-line treatment of metastatic colorectal cancer, followed by the approval from the EMA and other regulatory authorities." (PMID 38339258, 2024). "Clinically, bevacizumab, a recombinant humanized monoclonal antibody that neutralizes vascular endothelial growth factor-A (VEGF-A, or VEGF), is used in the first-line treatment of metastatic colorectal cancer (CRC) and produced significant survival improvement." (PMID 35985991, 2022). "Aflibercept is among the recombinant proteins targeting the VEGF signaling pathway; Aflibercept is a soluble recombinant VEGFR fusion protein that inhibits multiple VEGF family members (i.e., VEGFA, VEGFB, and PIGF) which has been approved for the treatment of metastatic colorectal cancer." (PMID 33171691, 2020).